VDAC1 (voltage dependent anion channel 1)
Diseases named in the same sentence as VDAC1 in open-access papers (continued):
Sharing a sentence is not in itself a finding about the gene and the disease.
cancer (continued). "Given VDAC1’s critical role in regulating metabolic and energy processes, targeting it offers a promising strategy for anti-cancer therapy." (PMID 39456237, 2024). "This VDAC1 overexpression in cancer is despite its involvement in apoptosis, where increased levels typically lead to apoptotic cell death." (PMID 39456237, 2024). "Immunofluorescence staining showed decreased expression of VDAC1 and metabolism-related proteins and altered expression of cancer stem cell markers." (PMID 39272828, 2024). "VDAC1 is overexpressed in various cancer cell lines and different tumors, pointing to its importance for their survival." (PMID 36900417, 2023). "Voltage-dependent anion channel 1 (VDAC1) is involved in cancer metabolism via its modulatory role in the transport of various metabolites." (PMID 36418670, 2023). "CoQ0 was also found to induce mitochondrial permeability transition pore (PTP) opening, which triggers apoptosis via ROS-mediated VDAC1 upregulation in cancer cells (HL-2), as well as tumor growth suppression in cancer-bearing mice." (PMID 37176145, 2023). "VDAC1 is a mitochondrial protein that contributes to the metabolic phenotype of cancer cells by regulating mitochondrial activity." (PMID 38067169, 2023). "The crucial role it plays in regulating the metabolic and energetic functions of mitochondria in cancer cells is demonstrated by findings that downregulating VDAC1 expression using siRNA decreases energy production and cell growth and inhibits tumor growth." (PMID 36900417, 2023). "This variable behavior of VDAC1 in different cancers was recently summarized as “the intersection of cell metabolism, apoptosis, and diseases”." (PMID 37046443, 2023). "It appeared that numerous human cancer cell lines exhibited either elevated or decreased VDAC1 expression if compared to normal cell lines." (PMID 37046443, 2023). "This loop governs the helical movement through the channel pore and inhibits the transition of VDAC1 into a closed state in cancer cells." (PMID 38202657, 2023). "The mitochondrial voltage-dependent anion channel 1 (VDAC1) protein is involved in several essential cancer hallmarks, including energy and metabolism reprogramming and apoptotic cell death evasion." (PMID 36900417, 2023). "HK2 is expressed on mitochondria in cancer cells and interacts with voltage-dependent anion channel 1 (VDAC1) to impede apoptosis." (PMID 37681030, 2023). "Among the top 20 proteins, Drp1 (alias DNM1L), TOM20 (alias TOMM20), and VDAC1 differed significantly in cancer progression." (PMID 37198593, 2023). "By interacting with the anti-apoptotic proteins Bcl-XL, Bcl-2, and HK, VDAC1 regulates cancer cell apoptosis and shields tumor cells from cell death." (PMID 36750173, 2023). "Using human and mouse VDAC1 recognizing siRNA (si-m/hVDAC1-B), we found that VDAC1 depletion inhibited cell proliferation, induced metabolism reprograming, altered the tumor microenvironment, eliminated cancer stem cells, and induced cell differentiation." (PMID 35883451, 2022). "We demonstrated that depleting VDAC1 in cancer cells led to metabolic re-programing and tumor regression and to disruption of tumor–host interactions." (PMID 35883451, 2022). "Next, we tested the effect of VDAC1 silencing on the expression of cancer stem cells (CSCs), a small subset of cells with the ability to self-renew and maintain tumor growth and recurrence after therapeutic intervention." (PMID 35883451, 2022). "VDAC1 expression is upregulated in numerous human cancer cell lines compared with that in normal cell lines, and VDAC1 is therefore a potential therapeutic target in cancer." (PMID 35215239, 2022). "Taken together, this pan-cancer analysis provides relatively comprehensive information on the potential value of VDAC1 as a prognostic biomarker and therapeutic target." (PMID 35958281, 2022).
cancer (continued). "The expression of VDAC1 is more abundant in cancer, A549, and HeLa cells, than in normal WI-38 fibroblasts derived from lung tissue, HCC tissues, HepG2 and SMMC7721 cells, as well as lung adenocarcinoma tumors." (PMID 35205604, 2022). "It should be noted that the decrease in VDAC1 level upon siRNA treatment is also a function of its degradation rate being different in different cancer cell lines." (PMID 35883451, 2022). "The results are consistent with tumor depletion of VDAC1, altering cell metabolism, including mitochondrial and glycolysis activities, in agreement with the concept that cancer cells use a combination of glycolysis and OXPHOS." (PMID 35883451, 2022). "Recently, VDAC1 expression was correlated with poor prognosis in human breast and lung cancer patients." (PMID 36232784, 2022). "As a gatekeeper of mitochondria, VDAC1 can decide the fate of cancer cells by regulating metabolic and energetic functions." (PMID 35729567, 2022). "VDAC1 expression is upregulated in several human cancer cell lines when compared to normal cell lines." (PMID 36686716, 2022). "Because of the functions of VDAC1 in cell metabolism and apoptosis, it is considered to be involved in the progression of cancer and is a potential anticancer therapeutic target." (PMID 35958281, 2022). "The effects of VDAC1 depletion on the interplay between metabolism and epigenetics can explain the multiple effect of its depletion in several cancer hallmarks." (PMID 35883451, 2022). "Current studies suggested that the possible mechanism of VDAC1 upregulation in cancer was related to providing metabolic advantages to tumor cells." (PMID 35958281, 2022). "By downregulating VDAC1, we targeted cell energy and metabolism and other cell functions essential for cancer cell survival." (PMID 35883451, 2022). "In summary, this pan-cancer analysis clarified the correlation between VDAC1 expression level and the prognosis of different cancer types." (PMID 35958281, 2022). "VDAC1 has also been found to be involved in anti-apoptosis by interacting with anti-apoptotic proteins overexpressed in cancer such as Bcl-2, Bcl-xL, HK, and mediating the release of Cytc to prevent the cancer cells from apoptosis." (PMID 35729567, 2022). "Initially, we evaluated the expression levels of VDAC1 in different types of human malignant tumors from the TCGA RNA-seq data via the TIMER." (PMID 35729567, 2022). "Third, this study only analyzed the clinical data related to VDAC1 protein expression in different cancer types." (PMID 35958281, 2022). "Future studies of VDAC1 at the cellular and molecular levels will help elucidate its value in cancer diagnosis and therapy." (PMID 35958281, 2022). "Our results suggest that cancer metabolic re-programming via VDAC1 depletion targets both the cancer and host compartment containing the tumor, remodeling the TME." (PMID 35883451, 2022). "Next, the cancer cases of the TCGA and GEO datasets were divided into high or low VDAC1 expression groups, and the correlation between VDAC1 expression and the prognosis of different tumors was investigated." (PMID 35958281, 2022). "As a key regulator of metabolic and energy reprogramming, disrupting cancer energy and metabolism homeostasis by VDAC1 depletion in tumor cells is thus expected to affect cancer development and survival." (PMID 35883451, 2022). "It has been reported that the overexpression of VDAC1 is related to many diseases including neurodegeneration, cardiovascular diseases, type 2 diabetes, and different types of cancers." (PMID 35729567, 2022).
cancer (continued). "One of the proteins controlling cell energy and metabolic homeostasis and apoptosis that is highly expressed in various cancer cell lines and different tumors is a mitochondrial protein, namely, voltage-dependent anion channel 1 (VDAC1)." (PMID 35883451, 2022). "VDAC1 expression was negatively corrected with neutrophils and macrophages, which play important roles in anti-cancer immunity." (PMID 35729567, 2022). "Multiple studies have indicated that VDAC1 is related to tumor progression, and molecules, peptides, and mRNAs targeting VDAC1 are potentially effective in cancer treatment." (PMID 35958281, 2022). "VDAC1 and the complex of glycolytic hexokinase regulate metabolites that provide a metabolic advantage to cancer cells through the outer membrane channels." (PMID 36042412, 2022). "VDAC1, as the mitochondrial gatekeeper and overexpressed in cancers, is critical for cancer progression, with its depletion inducing metabolic reprogramming and arresting tumor growth." (PMID 34200480, 2021). "It has been shown that the use of VDAC-1-specific small interfering RNA leads to the metabolism alteration and the growth suppression of cancer cells." (PMID 33536086, 2021). "In many types of cancer, the interaction of VDAC1 with HK, especially HK II, directly accesses to mitochondrial ATP for phosphorylation of glucose to glucose-6-phosphate and contributes to the cancer cells unrestricted growth and the inhibiting of apoptosis." (PMID 33680287, 2021). "VDAC1 participates in cancer metabolism via its modulatory roles in the transport of various metabolites." (PMID 33680287, 2021). "The results show alterations in the expression of key pathways related to metabolism both in those of human origin derived from human cancer cells (A549 cells) where VDAC1 was silenced and in those of mouse origin, representing the TME." (PMID 34200480, 2021). "While some level of TSPO and VDAC1 binding is needed to regulate the mitophagy pathway, overexpression of TSPO led to increased binding to VDAC1 which resulted in an accumulation of dysfunctional mitochondria in cancer cells." (PMID 34359907, 2021). "Here, by silencing the expression of VDAC1 specifically in cancer cells, we were able to modify their metabolism and view the effect on the microenvironment." (PMID 34200480, 2021). "Our results show that VDAC1 depletion in cancer cells within the tumor altered the TME on several levels." (PMID 34200480, 2021). "As a key regulator of metabolic and energy reprogramming, disrupting cancer energy and metabolism homeostasis by VDAC1 depletion in tumor cells is expected to also modulate the TME." (PMID 34200480, 2021). "Several studies show that VDAC isoform 1 (VDAC1) is the dominant isoform in most malignant tumors including CRC." (PMID 34381722, 2021). "ECM dynamics involving not only protein production but also their degradation were affected upon the depletion of VDAC1 in cancer cells." (PMID 34200480, 2021). "In cancer cells, VDAC-1 is a protein with dual function involved in the regulation of survival and mitochondria-mediated apoptosis." (PMID 33536086, 2021). "VDAC1, by regulating the metabolic and energetic functions of mitochondria, controls the fate of cancer cells." (PMID 34671273, 2021). "Metformin via interacting with VDAC1 and modulating its conductance it can affect cancer cell metabolism." (PMID 34671273, 2021). "In this context, VDAC1 has been defined as a pro-apoptotic protein and, for the same reason, it has rapidly become a pharmacological target, especially in cancer research." (PMID 34064816, 2021). "The mechanisms underlying metformin’s protective effects in several diseases, and the link between metformin, HK and VDAC1 are presented below (section “Cancer, Metformin, VDAC1, and HK”)." (PMID 34671273, 2021). "This is well demonstrated by silencing VDAC1 expression in cell lines and different cancer mouse models using specific siRNAs." (PMID 34671273, 2021).
cancer (continued). "The results provide insights into the relationship between the TME and metabolism and point to VDAC1 as a novel target not only for reprogramming cancer cells, but also for modulating TME components." (PMID 34200480, 2021). "Hexokinase 2 (HK2) can resist cancer cell apoptosis by expressing on mitochondria and binding to voltage-dependent anion channel 1 (VDAC1)." (PMID 33802591, 2021). "It was also reported that silencing of VDAC1 expression by siRNA inhibited the proliferation of several cancer cell lines (including CRC)." (PMID 34381722, 2021). "Here, we demonstrate that depleting the mitochondrial gatekeeper VDAC1 in human cancer cells in tumors led to metabolic reprogramming, inhibited tumor growth, and disrupted tumor–host interactions." (PMID 34200480, 2021). "The increased level of VDAC1/HKs complexes correlates with an increased glycolytic rate by which cancer cells tend to promote glycolytic metabolism over mitochondrial respiration even in the presence of oxygen." (PMID 34064816, 2021). "Intriguingly, the efficacy of VDAC1-based peptides has been proven over the years in different cancers by preclinical models." (PMID 33946271, 2021). "We demonstrate that depleting VDAC1 in cancer cells led to metabolic reprogramming, tumor regression, and the disruption of tumor–host interactions." (PMID 34200480, 2021). "In most mammalian cells, including cancer cells, VDAC1 and 2 are the most abundant isoforms, whereas VDAC3 is the least expressed, except for testis and spermatozoa." (PMID 34658929, 2021). "It is noteworthy that the impact of VDAC1 manipulation on cancer cell bioenergetics and survival stretches beyond its role in the trio." (PMID 34572262, 2021). "Our group showed the colocalization of VDAC1 and hexokinase II in cell cultures and clinical cancer samples by confocal microscopy imaging." (PMID 34381722, 2021). "Several mechanisms were suggested to regulate VDACs Ca2+ conductance in cancer: hexokinase specifically interacts with VDAC1 in cancer cells to promote metabolism and to reduce apoptosis." (PMID 33477936, 2021). "It has been demonstrated that VDAC1 acts a controvertial role in the prognosis of different malignant tumors." (PMID 33680287, 2021). "VDAC1 has been shown as a critical protein in cancer development and survival and many anti-cancer compounds were shown to mediates their activity via targeting VDAC1." (PMID 34671273, 2021). "The increase in VDAC1 expression levels by metformin can explain its pro-apoptotic effect relevant to cancer therapy." (PMID 34671273, 2021). "In this study, we focused on the effects of metabolic reprogramming via depleting specifically VDAC1 in the human cancer cell on the TME derived from a host mouse." (PMID 34200480, 2021). "The results point to VDAC1 as a novel target for both inhibiting tumor growth and modulating the tumor microenvironment, thus influencing cancer progression, migration, and invasion." (PMID 34200480, 2021). "The mitochondrial protein VDAC1, is a key regulator of metabolic and energy homeostasis that contributes to the metabolic phenotype of cancer cells." (PMID 32331482, 2020). "As a transporter of metabolites in the mitochondria, VDAC1 is a key regulator of the metabolic and energy homeostasis, contributing to the metabolic phenotype of cancer cells." (PMID 32331482, 2020). "Here, we show that using specific siRNA to deplete a tumor of VDAC1 not only led to reprograming of the cancer cell metabolism but also altered several epigenetic-related enzymes and factors." (PMID 32331482, 2020). "The importance of VDAC1 in cell energy and metabolism homeostasis is reflected in its over-expression in many cancers, and with down-regulation resulting in reduced metabolite exchange between mitochondria and cytosol and inhibited cell and tumor growth." (PMID 32331482, 2020).
cancer (continued). "A previous study showed that in cancer cells, VDAC1 opening induced by blocking cytosolic free tubulin binding promoted the flux of respiratory substrates and other metabolites across the OMM." (PMID 32901466, 2020). "The VDAC1-tubulin interaction, therefore, represents a new pharmacological target for the development of novel anti-cancer agents." (PMID 33114780, 2020). "We have previously demonstrated that tumors depleted of VDAC1 undergo metabolic reprograming, leading to a reduction of tumor growth, invasiveness, and angiogenesis, and the disappearance of cancer stem cells, while inducing tumor cell differentiation." (PMID 32331482, 2020). "VDAC1 is highly expressed in various tumors obtained from patients, and in tumors established in mouse models, as well as in cancer cell lines, providing supporting evidence for its significance in high energy-demanding cancer cells." (PMID 33114780, 2020). "On the other hand, AFR should be rapidly eliminated in the mitochondrial environment of cancer cells due to overexpressed Cyb5R3/VDAC1 and high cytosolic levels of NADH as an electron donor." (PMID 32411317, 2020). "On the other hand, AFR should be rapidly eliminated in the mitochondrial environment of cancer cells due to overexpressed Cyb5R3/VDAC1 [,9] and high cytosolic levels of NADH as an electron donor." (PMID 31678721, 2020). "In contrast to a substantial amount of knowledge of the role of VDAC1 in physiology and pathology of neuronal, cardiac, and cancer cells, very little is known about the role of VDAC1 in kidney physiology, injury, and regeneration." (PMID 32290153, 2020). "Our findings, show for the first time, that VDAC1 via metabolic reprograming reversing the well-known metabolic reprograming of cancer cells, involves epigenetic remodeling." (PMID 32331482, 2020). "We also conducted IP/WB to evaluate the potential effect of HKC8 on HKDC1/VDAC1 interaction in different cells, including normal HMECs cells and two kinds of cancer cell lines, HANK1 and SW480." (PMID 32203147, 2020). "As treatments that affect the degree of expression and/or oligomer formation of VDAC1 have been efficacious in a wide variety of models, targeting VDAC1 has vast therapeutic potential to modulate the biology of cancer and other diseases." (PMID 33114780, 2020). "In cancer cells, free tubulin predominantly inhibited two isoforms of VDAC, VDAC1 and VDAC2, while VDAC3 is minimally affected." (PMID 31963677, 2020). "VDAC1 is upregulated in a variety of human cancer cell lines, while VDAC2 is overexpressed in melanoma, mesothelioma, and thyroid cancer cells." (PMID 33171939, 2020). "Both silencing and upregulation of VDAC1 in various type of cancer cell lines can stimulate apoptosis." (PMID 32901466, 2020). "Can high doses of vitamin C attack cancer cells only by inhibiting Cyb5R3/VDAC1 and specific destruction of cancer mitochondria?" (PMID 31678721, 2020). "It is over-expressed in many cancer types, and silencing of VDAC1 expression induces an inhibition of tumor development." (PMID 32436862, 2020). "Overexpression of the Cyb5R3/VDAC1 appears to be a compensatory mechanism that protects cancer cells and their mitochondria by regulating AFR accumulation at “steady-state” conditions, while also maintaining the cytosolic NAD+/NADH ratio." (PMID 31678721, 2020). "On the other hand, by using taxol, a mitotic inhibitor preventing cancer cells from dividing, the proportion of ciliated VDAC1-ΔC cell was increased, resulting in a decrease in both glycolysis and respiration." (PMID 33238609, 2020). "In contrast, silencing VDAC1 expression was found to inhibit cancer cell growth and trigger metabolic rewiring in mouse xenograft models of human glioblastoma (U-87MG), lung cancer (A549), and triple negative breast cancer (MDA-MB-231)." (PMID 31159324, 2019).